INS (insulin)
Diseases named in the same sentence as INS in open-access papers (continued):
Sharing a sentence is not in itself a finding about the gene and the disease.
Obesity (continued). "Obesity is one of the key risk factors for hypertension, with the two conditions interacting through mechanisms such as insulin resistance, inflammatory responses, and activation of the renin-angiotensin system." (PMID 41398253, 2025). "Moderate–severe OSA in children with obesity is associated with impaired insulin clearance and hepatic insulin sensitivity." (PMID 40365648, 2025). "SCFAs also contribute to improved metabolic health and reduced obesity risk by enhancing insulin sensitivity and promoting the secretion of satiety hormones." (PMID 41568030, 2025). "Circulating APLN levels are higher in people with obesity and T2D and inversely associated with insulin sensitivity, suggesting either APLN resistance or increased secretion from adipose tissue." (PMID 40171198, 2025). "Puberty is associated with a decrease in insulin sensitivity in youth with normal-weight or obesity, predominantly in females." (PMID 40195232, 2025). "By affecting lipid metabolism and insulin sensitivity, it can also contribute to the development of conditions like diabetes and obesity – one of the main risk factors in the immunopathogenesis of EC." (PMID 41050662, 2025). "As expected, baseline TDD of insulin was higher among adults with obesity likely related to genetic mutations than among controls (median TDD of insulin: 0.68 vs. 0.46 units/kg/day, respectively)." (PMID 40004833, 2025). "In mouse models, OSM receptor deficiency leads to late-onset obesity, adipose tissue inflammation, and insulin resistance." (PMID 40076884, 2025). "In adults, postbiotics have been associated with improvements in insulin sensitivity, lipid metabolism, and low-grade inflammation, suggesting potential utility in obesity and related metabolic disorders." (PMID 41010468, 2025). "Conversely, endothelial TRPC1 overexpression significantly ameliorates obesity-associated metabolic dysfunction, as evidenced by reduced visceral fat deposition, enhanced insulin sensitivity, and restored thermogenic capacity in adipose tissue." (PMID 40568618, 2025). "Metabolic shifts associated with the modified microbiome in obesity encompass heightened energy extraction from food, increased lipogenesis, and insulin resistance." (PMID 39901991, 2025). "Individuals with obesity who maintain normal insulin sensitivity have lower risk of cardiometabolic comorbidities, making glycemic control an important metabolic health goal." (PMID 41431696, 2025). "Among different maternal metabolic risk factors, fasting maternal insulin levels in pregnant mothers with obesity at 18-20gw were associated with the abdominal/total FMr in newborns, a known predictor of cardiometabolic risk later in life." (PMID 40646607, 2025). "Secondary objectives include improvement in glycaemia (HbA1c, time in range) decrease in insulin requirements and reduction in comorbidities associated with obesity and T1D." (PMID 40130476, 2025). "Zinc is critical for immune function, antioxidant defense, and insulin signaling, yet obesity is frequently associated with low serum zinc due to poor dietary intake and altered zinc homeostasis." (PMID 41305652, 2025). "A comprehensive treatment for obesity should address not only weight loss, but also to the control of important cardiovascular risk factors such as insulin-resistance, atherogenic lipid profile and high blood pressure." (PMID 39899119, 2025). "Obesity is associated with a range of changes in metabolic cytokines and hormones, including leptin, gastrin, insulin, and certain central lipids." (PMID 40150457, 2025). "Adipogenesis impacts obesity or MetS since the dysregulated expansion of small adipocytes is associated with decreased insulin sensitivity." (PMID 40696355, 2025). "A previous study involving Asian individuals aged 30–70 years showed that decreasing insulin sensitivity associated with obesity was more pronounced in men than in women." (PMID 38501152, 2024).
Obesity (continued). "Blocking PVNGLP-1R→DVC synaptic release or ablation of GLP-1R in the presynaptic compartment increases food intake and causes obesity, elevated blood glucose, and impaired insulin sensitivity." (PMID 38559032, 2024). "In genetic rat models, such as leptin-receptor-deficient fa/fa rats, gene deletion leads to obesity, hyperlipidemia, and impaired insulin metabolism." (PMID 39339720, 2024). "Vegetable deficiency in the daily diet leads to masked obesity in the body, such as low-grade inflammation, insulin resistance, and abnormal lipid metabolism." (PMID 39830328, 2024). "For example, fat mass and obesity-associated (FTO) gene is essential for insulin secretion and beta-cell function, as indicated in in vitro studies using INS-1 cells and human pancreatic islets." (PMID 39769194, 2024). "For example, microglial CX3CR1 (C-X3-C motif chemokine ligand 1) signalling determine obesity susceptibility in mice and its deficiency induces inflammation and insulin resistance in adipose tissue." (PMID 38483771, 2024). "People with obesity have lower SAT, which worsens insulin response and encourages the development of T2D; therefore, at the same body mass index, insulin-sensitive obesity is associated with a smaller VAT depot, implying a greater proportion of SAT mass." (PMID 38928386, 2024). "Obesity-induced insulin resistance forces pancreatic β-cells to secrete more insulin, which is highly stressful to β-cells, and obesity-induced lipotoxicity causes β-cell failure." (PMID 38256005, 2024). "Oxidative stress is implicated in obesity and metabolic syndrome development, affecting insulin secretion and glucose transport in adipose tissue and muscles." (PMID 38672237, 2024). "In the study of obesity and insulin sensitivity, mutations in SERPINA12 and MRAP2 have caught our attention." (PMID 38676834, 2024). "Indolelactate was inversely associated with insulin levels and obesity, and positively associated with dyslipidemia." (PMID 38535334, 2024). "Several circulating molecules have been identified as obesity-associated biomarkers that can be classified into three main groups: adipokines, markers of the glucose-insulin pathway, and inflammatory markers." (PMID 38474344, 2024). "Again, the term Equine Metabolic Syndrome (EMS) is used to describe horses with insulin dysregulation, obesity, and/or localized fat deposits and other risk factors that increase the risk of laminitis." (PMID 38473112, 2024). "Together, the obesity-associated impairment of insulin and anabolic sensitivity contribute to pathophysiological consequences with ageing, including the decline of skeletal muscle mass and function, termed sarcopenia." (PMID 37801203, 2024). "The loss of thermogenic adipocytes appears in aging and in obesity and is associated with worsened insulin sensitivity and glycemic control." (PMID 38474057, 2024). "Abnormal adipokine production from adipose tissue, baroreceptor dysfunction, interaction with the renin–angiotensin–aldosterone system, and insulin resistance are among the causative pathways of SNS activation in obesity." (PMID 39457606, 2024). "It is involved in the synthesis of NAD and has been associated with the development of obesity, insulin secretion, lipid profile and inflammation, among others." (PMID 39683415, 2024). "Another study demonstrated a correlation between obesity and elevated insulin levels, which have been associated with adverse effects on key fertility indicators such as sperm quality and reproductive hormone levels." (PMID 38892561, 2024). "In particular, longer periods of obesity can cause a β-cell dysfunction in the pancreas, resulting in insufficient insulin secretion to maintain normal glucose homeostasis." (PMID 38833133, 2024). "Gut microbiota is inextricably linked to obesity and IR, and we found that valine induced insulin insensitivity, disrupted intestinal and hepatic tissue structure and enhanced lipid deposition." (PMID 38803448, 2024).
Obesity (continued). "When subjected to HFD these mice display resistance to HFD-induced obesity, along with associated conditions such as liver steatosis, insulin insensitivity, and glucose intolerance." (PMID 38725872, 2024). "To better understand the role of GHSR in β-cell function under obesity and aging, we examined the insulin secretion of β-cell-specific Ghsr-deficient (Ghsr-βKO) mice under HFD-induced obesity and during aging." (PMID 38794702, 2024). "First, we confirmed that the HFD was effective in reproducing the muscular effects reported previously, including insulin resistance and sarcobesity: the relative loss of skeletal muscle mass resulting from obesity." (PMID 38882396, 2024). "The researchers also assessed blood insulin levels, glucose, and insulin tolerance in lean and obese mice, observing that lean miR–181-deficient mice were more insulin-sensitive and protected against obesity." (PMID 39596385, 2024). "Obesity is known to cause chronic metabolic dysfunction, resulting in altered levels of insulin/glucose, leptin/adiponectin, and other hormones and adipokines in the blood." (PMID 38311726, 2024). "Loss of hepatic miR-33 improves glucose tolerance, insulin sensitivity, and dyslipidemia during obesity-driven MASLD." (PMID 39190492, 2024). "Adiponectin is a hormone that sensitizes insulin, and low levels of adiponectin are associated with obesity and MetS." (PMID 38737552, 2024). "Lifestyle factors such as overnutrition and obesity that stimulate insulin secretion are also risk factors for CRC." (PMID 39103728, 2024). "Adipokines, which are peptide hormones encoded by obesity genes and synthesized by adipose tissue, can modulate glucolipid metabolism, insulin sensitivity, and inflammatory response through autocrine, paracrine, or endocrine pathways." (PMID 40302954, 2024). "A long-term high-fat diet (HFD) cause obesity and infertility through hypothalamic inflammation and insulin resistance, leading to metabolic abnormalities and ovulation dysfunction." (PMID 39906039, 2024). "Obesity, which is a primary risk factor for sleep-disordered breathing, is linked to higher body weight, adiposity, decreased insulin sensitivity, hyperglycemia, and cardiometabolic risk factors." (PMID 39713783, 2024). "GLP-1RAs were associated with a lower risk for CRC in patients with obesity/overweight compared with insulin (HR, 0.50; 95% CI, 0.33-0.75), metformin (HR, 0.58; 95% CI, 0.38-0.89), or other antidiabetics." (PMID 38060218, 2024). "For example, ADF has been shown to exacerbate atherosclerosis in mice predisposed to the condition, and TRF increases hepatic insulin resistance in young rats with diet-induced obesity." (PMID 39104461, 2024). "cDIP also displays some similarity (33% identical, 23% similar amino acids) to Leucine-rich alpha-2-glycoprotein 1 (LRG1) a secreted obesity-linked cytokine that regulates insulin signaling." (PMID 39483909, 2024). "Paradoxically, this heightened insulin sensitivity results in a substantially reduced risk of developing type 2 diabetes, while increasing the susceptibility to obesity and cancer." (PMID 38792950, 2024). "Its deficiency has been associated with enhanced insulin sensitivity and improved serum lipid status, making it a potential target for obesity treatment." (PMID 38405061, 2024). "In conclusion, obesity is associated with insulin dysregulation and altered skeletal muscle metabolism in older mares." (PMID 38886475, 2024). "The expression of SERPINA12 was positively correlated with obesity and insulin sensitivity, while mutations in MRAP2 were significantly associated with increased obesity risk." (PMID 38676834, 2024). "A high‐fat diet combined with streptozotocin (HFSTZ) has been shown to induce obesity‐associated oxidative stress, neuronal insulin resistance, glial cell activation, and neuroinflammation, which are important risk factors for neurodegeneration." (PMID 39690860, 2024).
Obesity (continued). "Evidence suggests that PCOS is linked to impairments in insulin sensitivity and secretion, which are worsened by the presence of obesity." (PMID 39070348, 2024). "Inhibition of cilia motility impaired Calcium (Ca2+) influx and insulin secretion and cilia-related genes have been shown to be dysregulated in T2D patients and associated with obesity." (PMID 38685053, 2024). "Substance P is a neurotransmitter associated with obesity development and impairment of insulin signaling." (PMID 38612572, 2024). "Changes in the production of short-chain fatty acids and improvements in gut barrier integrity are linked to enhanced insulin sensitivity and reduced inflammatory markers, essential for effective obesity management." (PMID 39452088, 2024). "Cross-sectional studies suggest that higher fat intake is associated with impaired insulin sensitivity, although this association is primarily attributed to obesity." (PMID 38612972, 2024). "In conclusion, LGA conceived from ART were at a higher risk of cardiovascular metabolic dysfunction in childhood, were more predisposed to obesity, and had decreased insulin sensitivity." (PMID 38764021, 2024). "A moderate weight loss of 5–10% in people with obesity leads to improvement in metabolic function, such as abdominal fat reduction and enhanced insulin sensitivity." (PMID 38674919, 2024). "Obesity is linked to impaired insulin signaling, partly due to inflammatory signals generated within adipose tissue." (PMID 38807790, 2024). "It promotes a diverse range of nutrients while restricting the consumption of detrimental components, such as excessive sugars and saturated fats, which are associated with impaired insulin sensitivity and increased obesity risk." (PMID 39834470, 2024). "The genetic predisposition to type 2 DM is associated with genes controlling insulin secretion and function, as well as genes influencing factors like susceptibility to obesity." (PMID 39605770, 2024). "The available data indicate that a 5% weight loss in women with obesity results in significant improvements in endocrine parameters, including decreased levels of free testosterone, LH, and insulin, as well as increased ovulation frequency." (PMID 38892561, 2024). "Dietary patterns are key components associated with a higher incidence of obesity, particularly those containing fast-absorbing carbohydrates, which increase insulin concentrations attributed to hyperinsulinemia and IR." (PMID 38268038, 2024). "Patients with obesity exhibit a distinctive metabolic profile imbalance that is linked to significant changes in insulin sensitivity, inflammatory responses, and other molecular modifications, increasing the risk of developing metabolic diseases." (PMID 39179677, 2024). "Although an association between obesity before pregnancy and the need for insulin treatment has been reported previously, it is unclear what cutoff value of pregestational BMI influences insulin utilization during pregnancy." (PMID 39803116, 2024). "We and others have previously reported that IFNγ levels are elevated in individuals with obesity and obese animals, and reduced IFNγ levels are associated with improved insulin action and glucose metabolism." (PMID 38951527, 2024). "The Bogalusa Heart Study revealed that both childhood obesity and IR can predict adult MetS development, but after adjustment for insulin and BMI respectively, only obesity maintained a significant association." (PMID 38133765, 2024). "Obesity and overweight are considered the primary accelerators for the T2D inflammatory component inducing progressive loss of beta cell insulin secretion with coexisting insulin resistance." (PMID 38564266, 2024). "Changes in lipid and insulin profiles were observed to be closely associated with complicated metabolic dysfunction, such as abnormal glucose tolerance, dyslipidemia, and obesity." (PMID 38745759, 2024).
Obesity (continued). "The mechanisms by which polyphenols combat obesity are multifaceted, but the neurohormones in the brain that control insulin linked to hunger and fullness are the most studied field." (PMID 38397458, 2024). "The main finding of the present study was that ω-3 PUFA supplementation reverses obesity-associated insulin signaling dysfunction in soleus skeletal muscle." (PMID 38399437, 2024). "Several studies have shown that LCHFD consumption significantly decreases insulin levels while WD consumption is associated with obesity development and high insulin levels." (PMID 38474774, 2024). "This underscores the potential of TyG-related obesity indices for identifying periodontitis risk, and emphasises the importance of fat distribution and insulin resistance in the pathogenesis of periodontitis." (PMID 38970059, 2024). "A few studies suggest that anthocyanins regulate obesity and insulin sensitivity associated with adiponectin and leptin secretion and PPARγ activation in adipocytes." (PMID 38254596, 2024). "Of note, LINK‐A LNAs treatment alleviated obesity and metabolic disorders in mice, as evidenced by weight loss, reduced fasting glucose, and increased insulin sensitivity." (PMID 38145352, 2024). "T2DM is a complex metabolic disorder that is related to changes in lipid metabolism and pancreatic β-cell dysfunction caused by obesity, leading to insufficient insulin secretion and IR." (PMID 38560269, 2024). "Recent studies show a lower risk of certain obesity-associated cancers when compared to metformin and insulin over the span of 15 years." (PMID 39335195, 2024). "The most associated phenotypes were obesity and insulin sensitivity traits, in line with the established contributions of ASPC transcriptomic profiles to the dysmetabolic adipose tissue states observed in obese and type 2 diabetic individuals." (PMID 38297378, 2024). "Obesity is associated with several metabolic alterations in the host, including glucose, lipids, insulin, adipokines, cytokines, and chemokines." (PMID 39466902, 2024). "Weight loss through a VLCD caloric restriction is an effective strategy for reducing CDV risk, as it ameliorates the lipid profile, insulin resistance, and inflammatory response in subjects with obesity." (PMID 39061938, 2024). "Both human T2D and feline diabetes show a strong association with obesity, insulin resistance and impaired insulin secretion by β-cells." (PMID 38785817, 2024). "Excessive insulin secretion inhibits fat breakdown and promotes pre-adipocyte differentiation, ultimately increasing the risk of obesity." (PMID 38540910, 2024). "Metabolic abnormalities in carbohydrates, lipids, and protein metabolism are associated with insulin alterations in individuals with obesity." (PMID 38248457, 2024). "We found parental obesity to be associated with unhealthier outcomes in children, as reflected in increased blood insulin levels and reduced insulin sensitivity, unfavorable lipid profile, and pro-inflammatory milieu." (PMID 38238301, 2024). "Chronic inflammation linked to obesity is recognized as a key factor contributing to diminished insulin sensitivity." (PMID 39408777, 2024). "Obesity and low insulin levels are determinants of MetS, which is associated with a positive metabolic phenotype." (PMID 39731011, 2024). "Hyperleptinemia and leptin resistance are closely associated with obesity and T2D, and lower leptin concentrations in circulation are correlated positively with improved insulin sensitivity, lipid metabolism, lower adiposity, and inflammation." (PMID 38610754, 2024). "Knocking out Thbs1 in AT can inhibit tissue inflammation caused by obesity and improve tissue insulin sensitivity." (PMID 38764083, 2024). "Individuals with T1D often have obesity rates comparable to their age-matched peers at diagnosis and are at risk for further weight gain due to systemic insulin therapy, frequent snacking to manage hypoglycemia, and reduced physical activity." (PMID 39605938, 2024).